RN7SL654P (RNA, 7SL, cytoplasmic 654, pseudogene)
Gene: Miscellaneous RNA gene on chromosome 1 (184,335,658 to 184,335,949, forward strand). Ensembl gene ENSG00000244568.
Homologues: Orthologues: chimpanzee Metazoa_SRP (99% identical), macaque Metazoa_SRP (90% identical). Paralogues in human: RN7SL1 (82% identical), RN7SL3 (82% identical), RN7SL2 (82% identical), RN7SL126P (79% identical), RN7SL220P (79% identical), RN7SL47P (79% identical), RN7SL630P (79% identical), Metazoa_SRP (79% identical), RN7SL218P (79% identical), RN7SL678P (79% identical), RN7SL786P (79% identical), RN7SL242P (79% identical), and 702 more.